TLR4 (toll like receptor 4)
Diseases named in the same sentence as TLR4 in open-access papers (continued):
Sharing a sentence is not in itself a finding about the gene and the disease.
colitis (continued). "In the case of colitis development associated with TLR4 signaling, constitutively active TLR4 in epithelial cells did not induce mucosal inflammation in villin-TLR4 transgenic mice." (PMID 37519301, 2023). "Together, these data indicate that the failure of TLR4-SNP mice to resolve DSS-induced colitis may be secondary to their failure to induce “tissue repair” M2a Mφ." (PMID 37768050, 2023). "Since naringenin is the major compound in EV extract, this may explain its inhibitory effects on the TLR-4/NF-kB axis and ameliorating impact on AA-induced colitis." (PMID 37895902, 2023). "Inhibition of the TLR4 pathway activation may be a feasible option for treating colitis, considering its detrimental impact on health." (PMID 38231750, 2023). "By blocking the S100-PRR interaction, rCT-S100A8/9 can improve colitis while retaining the TLR4-dependent antibacterial defense mechanism, which may become a potential therapeutic target for CAC." (PMID 38273841, 2023). "The PCSK9 inhibitor could inhibit the activity of TLR4/NF-κB to ameliorate colitis induced by 2,4,6-trinitrobenzene sulfonic acid." (PMID 37350960, 2023). "Previous studies reported that TLR4−/− mice are more sensitive to DSS-induced colitis than WT mice." (PMID 37768050, 2023). "We hypothesized that therapeutic administration of rosiglitazone would also contribute to the resolution of DSS-induced colitis in the TLR4-SNP mice." (PMID 37768050, 2023). "Previous study has found that in DSS-induced colitis, TLR4-NF-κB are overexpressed." (PMID 37125181, 2023). "On the other hand, TLR4 over-expression is associated with increased levels of inflammatory mediators, such as TNF-alpha, cyclooxygenase (COX)-2, and IL-12, with a higher susceptibility to both acute colitis and colitis-associated CRC." (PMID 37998389, 2023). "Even prior to the identification of TLR4 as the LPS sensor, inbred mouse strains that exhibited LPS unresponsiveness (e.g., C3H/HeJ and C57BL/10ScN) also differed in susceptibility to dextran sodium sulfate (DSS)-induced colitis." (PMID 37768050, 2023). "The anti-colitis mechanisms of Eckol might be attributed to the down-regulation of the TLR4/NF-κB/STAT3 pathway, inhibition of inflammation and apoptosis, as well as its immunoregulatory activity." (PMID 37504907, 2023). "In response to DSS, colons of TLR4-SNP mice produced reduced levels of M2a Mφ marker mRNA and protein, including PPARγ, and therapeutic administration of the PPARγ agonist ligand, rosiglitazone, resolved colitis in TLR4-SNP mice, and increased expression of the M2a protein, Ym1." (PMID 37768050, 2023). "Furthermore, eriodictyol modulated TNBS-evoked TLR4/NF-κB path excitation, thus suppressing the progress of colitis." (PMID 36937890, 2023). "Moreover, glycated casein by TGase-type and casein inhibited the activation of the TLR4/NF-κB signaling pathway as a protective mechanism against DSS-induced colitis." (PMID 37761139, 2023). "Therefore, inhibiting the TLR4/MyD88/NF-κB signaling pathway is an attractive approach for the therapy of colitis." (PMID 36193153, 2022). "Notably, rCT-NAMPT has a partially therapeutic effect against acute DSS-induced colitis in TLR4−/− or CYBB−/− mice compared with WT mice." (PMID 36552583, 2022). "The effects of melatonin in colitis may be related to detecting bacteria in the gut lumen with TLR4, alteration of goblet cells, and regulation of antimicrobial peptides (AMPs)." (PMID 36101343, 2022). "TLR4 expression is markedly elevated in DSS-induced colitis model mice." (PMID 36450854, 2022). "Regulation of the TLR4/MyD88/NF-κB signaling pathway may be an important mechanism for the treatment of colitis inflammation in mice." (PMID 35630568, 2022). "After induction of experimental colitis, the relative expression levels of CD-4, CD-8 and TLR-4 were significantly downregulated with increasing concentrations of QT-NPs, unlike the colitic non-treated group, which exhibited higher expression levels of these genes." (PMID 35884960, 2022).
colitis (continued). "This, in addition to the inhibitory effect of TLR4 on SIRT1 levels and its proven role in ROS production, supports the hypothesis that TLR4/NF-κB/NLRP3 inflammasome signaling is the keystone in the inflammatory events encountered in DSS-induced colitis." (PMID 35631426, 2022). "In summary, our results indicated that central administration of HO exhibited anti-inflammatory effect and effectively alleviated DSS-induced colitis in mice by inhibiting TLR-4/NF-κB pathway-mediated pro-inflammatory response and improving intestinal barrier function." (PMID 36176442, 2022). "Interestingly, IL-33 protects against haptenizing molecule 2,4,6-trinitrobenzene sulfonic acid-induced colitis in mice by enhancing autophagy through the TLR4-dependent signaling pathway." (PMID 36129262, 2022). "In addition, baicalein administration remarkably suppressed the phosphorylation of NF-κB p65 and IκBα in the colon of TNBS-colitis mice, which was in accordance with the inhibitory effects on the protein expression of TLR4 and MyD88." (PMID 35805952, 2022). "Third, we show here that the eNAMPT–CYBB and –TLR4 axes contribute to the pathogenesis of colitis." (PMID 36552583, 2022). "FM(TLR4−/−)→WT and FM(TLR4−/−)→TLR4−/− mice exhibited similar colitis phenotypes." (PMID 35761415, 2022). "TLR4 deficiency resulted in significantly reduced acute NF-κB signaling, inflammation, and COX-2 expression in a preclinical model of dextran sulfate sodium (DSS)-induced colitis." (PMID 35719331, 2022). "In contrast, another study reported MT’s positive outcomes in TNBS (trinitrobenzene sulfonic acid)—induced colitis in mice are mediated by the inhibition of inflammation through the down-regulation of the TLR4/Myeloid differentiation primary response 88 (MyD88)/NF-κB pathway." (PMID 36421432, 2022). "Since ILK mediates activation of the TLR4/NF-κB/TNF-α signaling pathway by LPS (a TLR4 agonist) in colitis, it is possible that ILK could have an impact on regulating the activities of different TLRs in cancer." (PMID 34163519, 2021). "Notably, curcumin significantly decreased the percentage of CD11b+F4/80+TLR4+ macrophages and inhibited the expression of TLRs/MyD88 signaling molecules and their downstream proteins in colitis mice." (PMID 34567209, 2021). "Accordingly, acute administration of liraglutide may attenuate intestinal tight junction gene levels via an LPS- and TLR4-dependent mechanism and promote BT under stress conditions, such as those found in the colitis model." (PMID 33911125, 2021). "This study showed that B. lactis XLTG11 could alleviate DSS-induced colitis in mice including regulating inflammatory cytokines, protecting intestinal barrier function, inhibiting TLR4/MYD88/NF-κB activation, and modulating the specific gut microbiota." (PMID 34683415, 2021). "Therefore, it has been suggested that butyrolactone-I alleviates inflammatory responses in LPS-stimulated IPEC-J2 and DSS-induced murine colitis by TLR4/NF-κB and MAPK signal pathway." (PMID 34660669, 2021). "It had been reported that L. rhamnosus GG or L. rhamnosus GG-derived factors could attenuate the inflammatory response induced by activation of TLR4/NF-κB in the colitis." (PMID 34684320, 2021). "Importantly, TLR4 KO mice exhibit increased sensitivity to experimental colitis, along with various other TLRs and related receptors and signaling molecules." (PMID 33805697, 2021). "Additionally, curcumin significantly downregulated CD11b+F4/80+TLR4+ macrophages and the protein levels of TLR2, TLR4, MyD88, NF-κBp65, p38MAPK, and AP-1 in colitis mice." (PMID 34567209, 2021). "A recent report has evaluated the protective effect of pinocembrin on colitis, whereby it suppresses gut microbiota and toll like receptor 4/myeloid differentiation factor 2/NF-κB pathway but enhances the intestinal barrier by upregulating the expression of tight junction proteins." (PMID 33669855, 2021).
colitis (continued). "Dietary intake of βGl and βGh diminished colitis by the time-dependent modulation of autophagy and apoptosis, which involved TLRs (TLR4, TLR5) and Dectin-1 receptor activation, with βGI having a stronger effect on apoptosis (Caspase 3 expression) and βGh on autophagy (LC3B expression)." (PMID 33923129, 2021). "Further gain- or loss-of-function experiments demonstrated the gradually upregulated TLR4 during CAC development might not only act as a biomarker, but also play an important role in promoting colitis-associated tumorigenesis." (PMID 34479599, 2021). "Interestingly, the percentage of CD11b+F4/80+TLR4+ macrophages in colitis mice increased significantly, whereas curcumin administration treatment resulted in a significant decrease in the percentage of CD11b+F4/80+TLR4+ macrophages." (PMID 34567209, 2021). "Furthermore, CLP-0611 inhibited the TLR4-linked NF-κB and AMPK signaling pathways, polarizing M1 to M2-like macrophages and thereby ameliorating colitis." (PMID 34567209, 2021). "It was found that IAP protected against colitis in mice in a TLR4-dependent manner." (PMID 34944428, 2021). "Paeoniflorin (PF) is a bioactive monoterpene glycoside extracted from Radix Paeoniae Rubra, which could inhibit colitis by inhibiting the expression of Toll-like receptor 4 (TLR4) and liver fibrosis by inhibiting macrophage activation." (PMID 34437444, 2021). "Moreover, TLR4 was implicated in Blimp-1 upregulation, which subsequently leads to Blimp-1-mediated NLRP12 downregulation and IL-1β secretion in DSS-induced colitis mice." (PMID 34299198, 2021). "In addition, the Toll-like receptor 4 (TLR4) was activated, which caused the elevation in the level of its ligand LPS on DSS-induced colitis." (PMID 34867926, 2021). "Notably, the dietary phytosterol, β-Sitosterol, which is structurally related to cholesterol and found in plant cell membranes ameliorates HFD-induced colitis in C57BL/6 mice by inhibiting LPS binding to TLR4 in the NF-κB." (PMID 33603741, 2020). "TLR4/MyD88 pathway and amelioration of the epithelial tight junctions might partly explain the beneficial effect of EA on colitis." (PMID 32419794, 2020). "Weight loss during DSS colitis in CD- or HSD-fed TLR4-deficient mice was not as pronounced as in wild-type (WT) mice." (PMID 33339337, 2020). "Several studies have proposed that a high expression of TLR-2 and TLR-4 may be associated with IBD pathogenesis, and ultimately can modulate the host’s susceptibility to colitis." (PMID 32872480, 2020). "In the present study, we aimed to investigate whether pinocembrin exert modulating effects on colitis mice via inhibiting the over-activation of TLR4/MD2/NF-κB signaling pathway." (PMID 32687156, 2020). "In conclusion, our work presented evidence that pinocembrin attenuated DSS-induced colitis in mouse, at least in part, via regulating intestinal microbiota, inhibiting the over-activation of TLR4/MD2/NF-κB signaling pathway, and improving the barriers of intestine." (PMID 32687156, 2020). "Because toll-like receptor 4 (TLR4) is implicated in HMGB1-mediated immune cell activation, DSS colitis was also elicited in TLR4-deficient mice in the presence and absence of HnAb." (PMID 33193406, 2020). "Exogenous HA acting through TLR2/TLR4 promotes wound repair in DSS colitis." (PMID 33552081, 2020). "This suggests that TLR4 activation by endogenous HA promotes healing in DSS colitis." (PMID 33552081, 2020). "Along with the increase in DSS-induced colitis, a significant increase in the expression of pro-inflammatory genes such as IL-6, TLR4, Cox2 along-with infiltration of CD45+ and CD45+F4/80+ immune cells were observed in HNE + DSS treated mice compared to DSS-alone." (PMID 31781341, 2019). "In support to this notion, we previously reported that CRH may protect against colitis through regulation of the toll-like receptor 4 (TLR4) expression." (PMID 31614860, 2019).
colitis (continued). "In an analogy, herewith we showed that during the induction phase of DSS-induced colitis Gal-3 deficient macrophages were not able to optimally produce IL-1β upon TLR4:LPS stimulation which led to their polarization towards immunosuppressive M2 phenotype." (PMID 31336879, 2019). "Therefore, it is necessary to evaluate the effects of TLR4 signaling in DSS-induced colitis for studying UC in detail." (PMID 31207873, 2019). "Likewise, TCS was very recently found to increase Tlr4 expression to promote colitis and aggravate colitis-related cancer in C57BL/6 mice." (PMID 31191794, 2019). "We showed that mice deficient in CRH were more susceptible to DSS-induced colitis, possibly due to overproduction of IL-12 and prostaglandin E2, while having significantly decreased TLR4 levels before, but not after the colitis induction." (PMID 31614860, 2019). "We aimed to determine whether lymphatic disruption in the mouse model of DSS-induced ileitis/colitis, was in portion driven by TLR4." (PMID 30972059, 2019). "TLR4-modulated signaling further activates NF-κB, which is followed by expression of an array of subsequent genes participating in inflammatory signaling cascades that mediate the pathogenesis of colitis." (PMID 30013563, 2018). "However, the induction of these genes was attenuated in TLR4 knock out mice, indicating a lower response to colitis induction." (PMID 30478292, 2018). "Importantly, it was found that POS showed an anti-colitis effect that appears to be related to its ability to downregulate COX-2 of TLR4/NF-κB pathway." (PMID 30013563, 2018). "In addition, milk oligosaccharide derivative sialyl(α 2,3) lactose has been shown to promote intestinal inflammation through interaction with toll-like receptor 4 in a mouse model of colitis." (PMID 29719535, 2018). "DSS-induced colitis significantly increased TLR-4, TLR-9, and MBL-C expression in colon tissues." (PMID 29463799, 2018). "TLR4 expression is reduced in enteric glial cells by the endocannabinoid-related lipid ligand palmitoylethanolamine, in a PPARα-dependent manner, to inhibit NF-κB activation, which is associated with a reduction in severity of DSS colitis." (PMID 29515999, 2018). "Colitis rats exhibited a remarkable tendency to up-regulate the target proteins (P < 0.05, P < 0.01), while CP could notably lower the levels of pp65, TLR4, p-STAT3, and p-JAK2 (P < 0.05, P < 0.01, P < 0.001)." (PMID 30042683, 2018). "Additionally, TLR4 expression is increased in colonic mucosa from mice with experimental colitis as well as in intestinal epithelial cells from patients with IBD27,28." (PMID 29180692, 2017). "Furthermore, the TLR4-specific inhibitor TAK-242 reduced the incidence of colitis upon DSS treatment." (PMID 29228570, 2017). "There is sufficient evidence that TLR4 is a key inducer of colitis and CAC." (PMID 29228570, 2017). "TLR4 expression has been shown to be upregulated in the colonic mucosa of DSS-induced colitis." (PMID 28848431, 2017). "These metabolites may ameliorate inflammatory diseases, such as colitis, by inhibiting the binding of lipopolysaccharide to toll-like receptor 4 on peritoneal macrophages and restoring the Th17/Treg cell balances." (PMID 28287423, 2017). "Cohousing with villin-TLR4 mice increases the sensitivity of WT mice to DSS-induced colitis." (PMID 26755160, 2016). "Thus, as we have seen in TNBS-induced experimental colitis, a decrease in Cav-1 levels results in a higher TNF output, possibly due to a loss of TLR4 regulation." (PMID 25756273, 2015). "Interestingly, IL-10 and TLR4 double knockout mice have an accelerated colitis development compared to IL-10 and TLR9 double knockout and IL-10 single knockout which do not develop colitis." (PMID 23382912, 2013). "Various authors have carefully and convincingly demonstrated that mice lacking TLR4 have increased susceptibility to the development of colitis, suggesting that TLR4 plays a protective role in this disease." (PMID 23762089, 2013).
colitis (continued). "TLR4 antagonists may reduce the incidence of CAC in patients with UC but may delay mucosal healing if colitis is in an active phase." (PMID 24212947, 2011). "Interestingly, TLR4 signaling induces these EGFR ligands with different kinetics throughout the course of colitis." (PMID 24212947, 2011). "TLR4 plays an important role in the intestinal inflammatory response because it is activated either by lipopolysaccharide (LPS) produced by colonic bacteria or saturated fatty acids (FAs), both of which were present in the Colitis + HFD animals." (PMID 22073943, 2011). "Mice ablated of TLR2, TLR4, TLR9, or their common adaptor molecule MyD88, were more acutely susceptible to colitis induced by the chemical colitogen dextran sodium sulfate (DSS), due in part to impaired protective responses and reduced prostaglandin production." (PMID 20885960, 2010). "LPS is a known agonist of toll-like receptor 4 signaling that plays a critical role in colitis." (PMID 20423518, 2010). "A brief report previously proposed that absence of TLR4 drives aggressive development of spontaneous colitis-associated adenocarcinoma in IL-10−/− mice, but detailed investigations of the underlying mechanisms are so far lacking." (PMID 20803699, 2010). "Furthermore, TLR-mediated sensing of gut bacteria has been suggested to play a role in intestinal homeostasis and TLR4 was shown to limit bacterial translocation during colitis." (PMID 17653282, 2007). "Furthermore, reduced macroscopic signs of colitis in TLR2-/-, TLR4-/-, and TLR2/4-/- were associated with diminished inflammatory activity as demonstrated by lower IFN-gamma concentrations in colonic mesenteric lymph nodes." (PMID 17653282, 2007). "Thus, TLR4 participates in the intestinal immune response to luminal bacteria and the development of colitis." (PMID 16351713, 2005). "Moreover, M2a macrophages are conductive to the resolution of DSS-induced colitis in TLR4-SNP mice." (PMID 40474676, 2025). "In conclusion, TLR-4 may be a key factor in the development of resistance to 5-FU chemotherapy in colitis-associated CRC, suggesting that the combined use of TLR-4 antagonists and regulation of the intestinal flora may provide potential ideas for further improving CRC treatment." (PMID 40404908, 2025). "In addition, SF4 (indole-3-carboxaldehyde) could inhibit intestinal inflammation on the TLR4/NF-kB/p38 signaling pathway, and balance amino acid metabolism in mice with colitis." (PMID 39330395, 2024). "In addition, the efficacy and mechanism of ruscogenin in ameliorating dextran sulfate sodium salt (DSS)-induced colitis by mitigating the extent of pyroptosis through regulating TLR4/NF-κB signaling pathway remains unclear and deserves further investigation." (PMID 38790951, 2024). "The effectiveness of similar polysaccharides like ASP-Ag-AP and GLP in reducing colitis via the TLR4/MyD88/NF-κB pathway suggests that EPS-LM, which also exerts anti-inflammatory effects through this pathway, may have comparable protective benefits against inflammatory conditions such as colitis." (PMID 39599671, 2024). "In conclusion, the research by Xia and colleagues revealed that L. plantarum AR113 and L. casei AR342 administrations might significantly elevate HO-1 expression, suggesting that some probiotics might prevent DSS-induced colitis via modifying the HO-1/TLR4/NF-κB pathway in mice colonic tissues." (PMID 39323474, 2024). "Therefore, this study was conducted to determine whether the aqueous extract of E. ulmoides leaves (AEEL) could alleviate cognitive dysfunction by regulating the JNK/TLR4 signaling pathway in DSS-induced colitis in mice." (PMID 38612870, 2024). "Furthermore, molecular mechanism studies revealed that the downregulation of the TLR4-MAPK/NF-κB signaling cascade may be closely related to the remission of colitis." (PMID 38474407, 2024).